SFRP2 (secreted frizzled related protein 2)
Diseases named in the same sentence as SFRP2 in open-access papers (continued):
Sharing a sentence is not in itself a finding about the gene and the disease.
tumor (continued). "Among the upregulated genes in CS1, SFRP2 and SFRP4 are Wnt-regulator and can modulate the differentiation of cancer-associated fibroblasts (CAFs), which contribute to the progression and metastasis of the tumor." (PMID 38549156, 2024). "The upregulation of SFRP2 in the tumor vasculature suggests a link between SFRP2 and angiogenesis." (PMID 39850884, 2024). "Additionally, methylated SFRP2 has been identified as a non-invasive biomarker for CRC detection, providing diagnostic value and the potential to predict tumor risk in surrounding normal mucosa." (PMID 38464391, 2024). "Targeting the identified subtype of fibroblasts or influencing SFRP2 gene expression in pericytes may offer new therapeutic strategies for combating this aggressive tumor." (PMID 39850884, 2024). "In the AEGJ liver metastasis group, SFRP2+ pericytes were closely associated with the angiogenesis-related VEGF pathway, suggesting that SFRP2+ pericytes may play a role in tumor angiogenesis-related pathways and mechanisms." (PMID 39850884, 2024). "For instance, designing specific inhibitors or gene regulation strategies to suppress SFRP2 expression in pericytes could mitigate its tumor-promoting effects within the microenvironment, thereby reducing metastatic potential." (PMID 39850884, 2024). "Therefore, we explored the sensitivity and specificity of combining RNF180 and SFRP2 with traditional tumor markers for detecting GC." (PMID 39541711, 2024). "Additionally, SFRP2, an upregulated glycoprotein in tumor vasculature, regulates Wnt signaling by binding to frizzled receptors on tumor endothelial cells, leading to angiogenesis through the noncanonical Wnt/Ca2+ pathway." (PMID 38474093, 2024). "The specific mechanism may involve high expression of SFRP2 in pericytes, promoting tumor angiogenesis and endothelial cell survival through the Wnt/Ca2+ signaling pathway, which contributes to AEGJ liver metastasis." (PMID 39850884, 2024). "Additionally, SFRP2 has been identified as a candidate tumor suppressor gene and a major contributor to tumorigenicity in colorectal, esophageal, and GC, where it is often silenced by promoter hypermethylation." (PMID 39541711, 2024). "We then co-stained for PKMYT1, TGF-α, SFRP1 and SFRP2 with the fibroblast markers: Collagen IVα1, PDGFR-α and α-SMA, which were respectively associated with ECM remodeling, immune modulation/M2 polarization and tumor proliferation/immune suppression." (PMID 37091166, 2023). "This study highlights the potential role of SFRP2 in tumor pathogenesis." (PMID 38069266, 2023). "In addition, the expression of secreted frizzled-related protein 2 (SFRP2), a member of the secretory glycoprotein family, correlates with the degree of immune infiltration of tumor cells and plays a synergistic role in tumor progression." (PMID 37405952, 2023). "At the molecular level, the high-risk score group had elevated expressions of tumor enhancing factors, including MMP7, and SFRP2, which may synergistically promote tumor growth, proliferation, invasion and chemoresistance." (PMID 36907877, 2023). "SFRP2 is a tumour suppressor in various cancers and an important suppressor for NSCLC invasion." (PMID 37999144, 2023). "This suggests that SFRP2 may act as a tumor suppressor in many cancer types, but recent studies have shown that SFRP2 could also act as a tumor promoter, depending on the cell type or cellular location." (PMID 36552843, 2022). "Since SFRP2 is specifically expressed in the urinary bladder and the contribution of stromal cell–tumor cell communication to UC progression remained to be determined, we were interested in exploring the role of SFRP2 in UBUC and UTUC, thereby improving prognosis and therapy." (PMID 35372028, 2022). "Accordingly, these observations suggest that SFRP2, a putative Wnt inhibitor, may function at the interactions between tumor cells and fibroblasts in UC development." (PMID 35372028, 2022).
tumor (continued). "Importantly, our results suggest that anti-SFRP2 therapy not only affects the tumor and endothelial compartments but also the tumor microenvironment through the calcineurin/NFATc3 signaling pathway, leading to a restoration of immunity." (PMID 34070758, 2021). "Indeed, SFRP2 is shown to be specifically upregulated in the tumor vasculature of several types of cancer." (PMID 33140138, 2021). "This provides evidence that SFRP2 expression is specific for blood vessels in the tumor." (PMID 33140138, 2021). "The effect of 5hmC has also been associated with tumour suppressor mechanisms: downregulation of TET1 and 5hmC were associated with transcription of SFRP2, which prevents tumour progression trough impairment of WNT pathway, that promotes EMT and cancer progression." (PMID 34944974, 2021). "On the contrary, SFRP2 is demonstrated to act as tumor suppressor in many other cancers, too." (PMID 34852024, 2021). "This further confirms that SFRP2 can play a role as tumor promotor." (PMID 33140138, 2021). "Together, these data provide evidence that SFRP2 can function as a tumor suppressor." (PMID 33140138, 2021). "Furthermore, the upregulation of sFRP2 in the tumor vasculature indicate that this stimulator can exert an angiogenic effect in a wide variety of human tumors." (PMID 34445494, 2021). "We also discovered several genes from the Wnt pathway with hypermethylation in EBVaGCs relative to LDs/normal tissues, including DKK3 (P = 0.0022), SFRP1 (P = 0.0034), and SFRP2 (P = 0.0005), and these genes have been reported to be frequently methylated and to function as tumor suppressors in NPCs." (PMID 34493320, 2021). "The increased insulin sensitivity in tumoral area could promote tumor growth in an independent Wnt signaling pathway (under dependent-insulin pathway), since SFRP2 is considered an adipokines that promotes insulin sensitivity and insulin resistance." (PMID 32517740, 2020). "Finally, when deepened in the study of the seven CpG islands of SFRP2 promoter of tumor colon area, the methylation of CpG sites 1, 2, 3, and 4 was significantly decreased in the > 30th group, when compared to the < 30th group (p < 0.05)." (PMID 32517740, 2020). "However, in CRC tumor tissue, the methylation of SFRP2 was moderately methylated, and higher circulating of vitamin D seems to have close relationship with low methylation rate." (PMID 32517740, 2020). "However, in > 30th CRC group, SFRP2 methylation was positively correlated with promoter methylation of TIAM1 in tumor area (p < 0.05)." (PMID 32517740, 2020). "However, within the non-treated patients, those with BMI > 25 showed significantly lower SFRP2 methylation levels, when compared to the BMI < 25 group, albeit only in the tumor samples." (PMID 31319558, 2019). "In the present study, we have specifically focused on the analysis of tumor and non-tumor samples for the methylation status of SFRP2 in an independent prospective cohort study, together with its association with the clinical and pathological features of CRC patients." (PMID 31319558, 2019). "SFRP2 DNA methylation in tumor samples was measured by pyrosequencing." (PMID 31319558, 2019). "Additionally, in the non-treated group, we observed higher SFRP2 methylation levels in patients with low BMI, suggesting a possible tumor suppressor role of SFRP2 in overweight/obese patients." (PMID 31319558, 2019). "Several studies suggest a decrease of Sfrp2 in a variety of cancers; further evidences indicate that Sfrp2 is able to inhibit the Wnt-induced increase in the levels of free β-catenin and influence inflammation and tumour cell proliferation." (PMID 30483664, 2018). "Based on our data on the decrease of apoptosis in Dox-induced muscle cachexia, we anticipate that sFRP2 could be a potential therapeutic target for cancer cachexia that is formed due to tumor formation." (PMID 30151071, 2018).
tumor (continued). "In the meantime, the reduced methylation status of DACT2, Wnt5A, and SFRP2 promoter was detected in TET1-CD-expressing tumor cells, with increased unmethylated sites at the promoter CpG regions, suggesting that TET1 really acts as a demethylase to renew expression of multiple TSGs in tumor cells." (PMID 30075814, 2018). "Moreover, our results indicate that while SFRP1 is lost in cancer cells via the process of DNA methylation, SFRP2 and 4 are likely derived from the tumour stroma, and thus tend to increase in tumours as compared to normal tissues." (PMID 28218291, 2017). "By subtracting the IgY-targeted ffc-TIC from the SFRP2-targeted ffc-TIC, we were left with the contrast signal that could be directly attributed to contrast retained in the tumor specifically by the SFRP2 antibodies." (PMID 28333964, 2017). "Despite production by tumour stroma, SFRP2 or 4 promoter gene methylation may still show promise as a cancer biomarker." (PMID 28218291, 2017). "Furthermore, expression of SFRP2 and 4 often increased in primary tumours compared to their normal counterparts, and this expression tightly correlated to tumour stromal content." (PMID 28218291, 2017). "On the other hand, a number of studies showed that sFRP2 promotes tumor progression." (PMID 27322325, 2016). "sFRP2, as a tumor suppressor, was shown to be inactivated by DNA methylation in RCC." (PMID 27322325, 2016). "By contrast, levels of SFRP1 and SFRP2 methylation were consistently elevated in lesions throughout the entire bowel, indicating that those genes are methylated, irrespective of tumor location or the molecular subtype of the tumor." (PMID 27145369, 2016). "For instance, sFRP2 is noted to be downregulated via epigenetic hypermethylation in human gastric cancer, colorectal cancer, and oral squamous cell carcinoma suggesting a role as a tumor suppressor." (PMID 27821163, 2016). "We specifically focused on the direct biological effects of sFRP2 on OS by using gain and loss-of-function experiments that revealed sFRP2 expression has no observable effect on tumor cell proliferation both in vitro and in vivo." (PMID 27821163, 2016). "However, in the corresponding normal tumor-adjacent tissues, the SFRP2 promoter was methylated in only three cases (6.12%)." (PMID 25189527, 2014). "Therefore, the results of the present study provide insight into the role of SFRP2 as a functional tumor suppressor in the development of OSCC through inhibition of the Wnt signaling pathway." (PMID 25189527, 2014). "There has been controversy in the literature as to whether SFRP2 is a tumor suppressor or promoter of tumor growth." (PMID 24489757, 2014). "However, as indicated by the tumor growth curve, the mean tumor volume was significantly smaller in the SFRP2-transfected nude mice than that in the animals inoculated with the Tca8113/pcDNA3.1 control (P<0.001)." (PMID 25189527, 2014). "Through our assumption that the anti-SFRP2 molecularly targeted contrast agents bind to endothelium in proportion to the amount of SFRP2 expressed, we hypothesize that we can detect whether SFRP2 expression increases or decreases during tumor growth." (PMID 24489757, 2014). "Overexpression of SFRP2 also effectively repressed tumor growth in xenograft animals." (PMID 25189527, 2014). "SFRP2 mRNA was detectable in 48 corresponding normal tumor-adjacent tissues (97.96%)." (PMID 25189527, 2014). "While conducting genomic profiling of breast tumor vascular cells obtained by laser capture microdissection, secreted frizzled related protein 2 (SFRP2) was identified as a gene with 6-fold increased expression in tumor endothelium as compared to normal vessels." (PMID 24489757, 2014). "Thus, the reduction of SFRP2 in SCC decreases collagen fibril deposition in the tumor stroma as it does in other tissue, facilitating invasive cell migration." (PMID 22384081, 2012).
tumor (continued). "Using linear regression we found four DNA methylation markers, MT2, SFRP2, TFAP2A, and TWIST1, that showed individual association with tumor subtype at p<0.05 significance level, however, after adjusting for multiple comparisons, none of these associations remained statistically significant." (PMID 22028801, 2011). "We hypothesized that MSCs could home to C4-2B tumors and secrete SFRP2 to inhibit tumor progression." (PMID 20886110, 2010). "Additionally, SFRP2 has been shown to play a key role in tumor angiogenesis." (PMID 37691636, 2023). "Therefore, sFRP4 and sFRP2 may play a tumor suppressor role in PAs, and their expression may serve as biomarkers of aggressiveness and prognosis in PAs." (PMID 37780610, 2023). "We observed that high SFRP2 expression in stroma but not in tumors is significantly linked to aggressive UC features, including high tumor stage and histological grade, positive nodal metastasis, the presence of vascular and perineural invasion, and high mitotic activity in UBUC and UTUC." (PMID 35372028, 2022). "Thus, whether antagonizing SFRP2 could overcome the tumor-induced inhibition of T-cell proliferation was investigated." (PMID 34070758, 2021). "Moreover, the tumour cells had hypermethylation in the SFRP2 promoter region." (PMID 28218291, 2017). "Thus, tumor hypoxia might stimulate SFRP2 and trigger both NF-kB dependent pathways and multiple angiogenic factors." (PMID 26485755, 2015). "Therefore, SFRP2 may be assigned a class II tumor suppressor gene in normal breast tissue, whose block of expression could be reversed by DNA demethylating (DNMT inhibitors) and histone reacetylating (HDAC inhibitors) drugs." (PMID 18990230, 2008). "SFRP2 can inhibit WNT-induced β-catenin dissociation, affecting cell cycle processes and tumor cell proliferation." (PMID 39729237, 2025). "SCFAs inhibit DNA methyltransferases (e.g., DNMT1), leading to demethylation and re-expression of tumor suppressor genes (e.g., SFRP2, WIF1), which in turn inhibit Wnt signaling and tumor growth." (PMID 41450947, 2025). "The spatial expression patterns of three key tumor stemness genes—REN, SFRP2, and AQP1—were examined in both tumor subtypes." (PMID 40534868, 2025). "Notable genes displaying similar expression patterns in AFCs and tumour cells compared with FCs included TFF3 and TG (signature genes of FCs), IGHG4 and SFRP2 (signature genes of FCs) and FN1 and SFTPA1 (signature genes of tumour cells)." (PMID 38426403, 2024). "The methylation levels of SFRP1, SFRP2, and Wnt inhibitory factor-1 (WIF1) in tumor tissues were found to be significantly upregulated compared to adjacent non-neoplastic tissues." (PMID 38464391, 2024). "We found that SFRP2 expression was mostly expressed in the NAT, although there was a small fraction of the tumor core and tumor border areas that showed a relative increase in SFRP2 expression." (PMID 38802858, 2024). "SFRP2 was identified as a regulator of the TME through its impact on Wnt signaling and tumor angiogenesis, while THBS4 influenced cancer stem cell-like properties in PCa via the PI3K/Akt pathway." (PMID 38672562, 2024). "In vitro data further supported the tumour suppressor role of AHRR and the pro-tumorigenic role of SFRP2." (PMID 38361045, 2024). "At cell level, we observed that SFRP2 was predominately expressed in stromal cells (located in the NAT area) and myofibroblasts (located in the tumor core and tumor border areas)." (PMID 38802858, 2024). "This aberration mainly results in the silencing of genes that contribute to DNA repair and tumour suppression, such as MLH1, CDKN2A, and SFRP2, hence promoting cancer growth and survival." (PMID 37953923, 2023).
tumor (continued). "Therefore, it is suggested that SFRP2 could play a tumour suppressor role in NSCLC." (PMID 37999144, 2023). "By contrast, other cell types beyond the tumor boundary, such as B cells, Macro-FOLR2, Myofib, and Fib-SFRP2, exhibited weak interactions in the tumor boundary niche." (PMID 36806082, 2023). "We observed that the concentration of SFRP2 was the highest in LCC, compared to SCC and AC, in tumour samples, as well as in NT specimens." (PMID 37999144, 2023). "We demonstrate expression changes also in Frizzled-related protein 2 (SFRP2), which is secreted and incorporated into ECM of the normal and tumor cells." (PMID 37239828, 2023). "Comparisons between NSCLC subtypes showed a significantly higher level of SFRP2 in LCC tumour samples compared to SCC (528.85 vs. 178.18; p = 0.021) and AC (528.85 vs. 116.57; p = 0.004) tumour samples, respectively." (PMID 37999144, 2023). "The expression of SLC27A2, SFRP2, KRT17 were up-regulated in tumor tissues (p<0.05), the expression of TAGLN was down-regulated (p<0.05), while those of NAT2 remained unchanged (p>0.05), compared with the levels in the corresponding normal tissues." (PMID 36479114, 2022). "Serum SFRP2 methylation was significantly correlated with poor differentiation grade, higher TNM stage with positive lymph node metastasis status and deeper tumor invasion in the bowel wall." (PMID 35055034, 2022). "We observed a continuous reduction from normal to primary tumor to metastatic tissues in the majority of our matched samples and a worse prognosis in patients of the FIRE 3 cohort with low SFRP2 expression." (PMID 35892888, 2022). "SFRP2 is a secreted factor reported to antagonize WNT signaling by sequestering of WNT ligands and has been connected with increased tumor growth, metastasis and therapy resistance, but has also been described as a tumor suppressor." (PMID 34021259, 2021). "Module-1 of the ENDCAP-C study showed that their panel of five markers (SFRP2, SFRP4, WIF1, APC1A, and APC2) was accurate in detecting pre-cancerous and invasive neoplasia and dysplasia." (PMID 34842672, 2021). "SFRP2 was significantly higher expressed in HBV (Hyperplastic blood vessels) and MVP (Microvascular proliferation) areas versus CT (Cellular tumor) areas." (PMID 34021259, 2021). "The expression of SFRP2, SFRP3, and SFRP4 in patients with GC significantly correlated with the clinical tumor stage." (PMID 34205081, 2021). "The analysis of the corresponding tumor and non-tumor samples also revealed upregulation of COMP, matrix proteins such as COL5A1, COL11A1, and FN1, and genes of the Wnt pathway (WNT7B, FZD10, SFRP2), while PLCB1, CAMK2B, PLCB4 and WIF1 are downregulated." (PMID 33227073, 2020). "In our study, SFRP2 promoter methylation in tumor area was positively correlated with insulin and HOMA-IR in tumor tissue from > 30th CRC patients, but also SFRP2 methylation in tumor-free area was correlated with HOMA-IR." (PMID 32517740, 2020). "SFRP2 methylation was also correlated with T cell lymphoma invasion and metastasis 1 (TIAM1) methylation in tumor area and CCAAT/enhancer-binding protein alpha (C/EBPα) in VAT." (PMID 32517740, 2020). "The SFRP1, SFRP2, and WIF1 methylation levels in tumor tissues were significantly higher than that in adjacent non-tumor tissues (P < 0.001)." (PMID 31830937, 2019). "The SFRP1, SFRP2, and WIF1 methylation levels in tumor tissues were significantly higher than that in adjacent non-tumor tissues (Mann-Whitney U test, P < 0.001)." (PMID 31830937, 2019). "Usually, as tumor-suppressor gene, SFRP1 and SFRP2 methylation were inversely correlated with the mRNA expression, and the expressions were increased after demethylation treatment in CRC cell lines." (PMID 31830937, 2019). "We aimed to evaluate the SFRP2 methylation status in both CRC tissue and adjacent tumor-free tissue from 75 CRC patients, by pyrosequencing after bisulfite treatment." (PMID 31319558, 2019).